HLA-C (major histocompatibility complex, class I, C)
Diseases named in the same sentence as HLA-C in open-access papers (continued):
Sharing a sentence is not in itself a finding about the gene and the disease.
leprosy (continued). "The protective effect of HLA-C*05 against in leprosy per se was recently described in a population in Rio de Janeiro, Brazil." (PMID 25605482, 2015). "This led us to evaluate if the CDSN and PSORS1C2 association with leprosy protection was independent of the HLA-C*07:06 allele." (PMID 34879060, 2021). "Conditioning the gene-wise analysis for the p.G36S, p.P94fs mutations or HLA-C*07:06 (allele with LD r2 between 0.7 and 1 with the two mutations in both cases and controls) the gene-wise association of CDSN or PSORS1C2 with leprosy lost significance (PSKAT-O ranging from 0.08 to 0.47)." (PMID 34879060, 2021). "The conditional analysis could not distinguish the association of CDSN/PSORS1C2 with leprosy from the HLA-C*07:06 protective effect." (PMID 34879060, 2021). "Indeed, a strong host genetic contribution to leprosy susceptibility has been well established through the identification of leprosy susceptibility genes by both positional cloning (PARK2, LTA, HLA-C, MRC1) and candidate gene approaches (e.g. TLR1, TNF, CUBN and NEBL)." (PMID 28793313, 2017). "The results showed decreased frequencies of HLA-C*05 and HLA-DRB1*07 in B leprosy patients when compared to the healthy control individuals, suggesting that they are associated with protection against B leprosy." (PMID 25605482, 2015).
acute GVHD (11 papers, 2011 to 2024). "Several publications have indicated that matching the amino-acid at position-116 in the HLA-C protein confers protection against the risk for acute GvHD." (PMID 25386183, 2014). "In a first attempt from the JMDP to disclose individual HLA-C mismatches with higher clinical relevance, seven HLA-C allele mismatched combinations were reported to confer a higher risk of acute GVHD." (PMID 24904572, 2014). "Four amino acid residues at positions 9, 99, 116, and 156 of HLA-C molecules were significantly associated with acute graft-versus-host disease (aGVHD)." (PMID 24904572, 2014). "Among these, residue 116 in the F pocket of the peptide binding groove has been identified as having a high frequency of mismatches that are responsible for adverse clinical transplant outcome, such as risk of acute GvHD and mortality, in comparison to HLA-C-matched donor-recipient pairs." (PMID 29470425, 2018). "HLA-C mismatches are clearly associated to alloreactivity after hematopoietic stem-cell transplantation; in a number of large cohorts, HLA-C mismatches are correlated to an increased risk of acute graft-versus-host disease (GVHD) or even impaired survival." (PMID 24860572, 2014). "Furthermore, patients presenting HLA-C-derived PIRCHE-I or more than one HLA-C-derived PIRCHE-II are at a higher risk of developing acute GVHD." (PMID 24860572, 2014). "The HLA non-coding SNPs have been associated with disease and regulation of infection such as the SNP in the 3′UTR of HLA-C associated to plasma HIV copy number and the SNP in the 3′UTR of HLA-DPB1 associated to acute GVHD." (PMID 30337930, 2018). "We failed to reveal possible sources of heterogeneity for TRM at HLA-DPB1 locus, and for chronic GVHD and acute GVHD (III-IV) at HLA-C locus." (PMID 28206973, 2017). "To this end, we analyzed the possibility to identify an alternative 9/10 mismatched donor for those HLA-C mismatched cases that had an increased probability of acute GVHD (i.e., PIRCHE-I > 0 and PIRCHE-II > 1, N = 17), using haplotype frequency tables." (PMID 24860572, 2014). "HLA-C mismatch at position 99 was reported to be associated with increased TRM and a C-mismatch at position 116 with increased risk of acute GVHD." (PMID 24904572, 2014). "While for HLA-A and -B, both antigenic as well as allelic mismatches are associated with an increased risk of acute GVHD, such an increased risk is only observed for antigenic HLA-C mismatches and not for allelic mismatches." (PMID 24860572, 2014). "For example, among the population with a single HLA-C mismatches, ASS at position 116 had a significantly increased risk of acute GVHD (III-IV), compared with those without the AAS." (PMID 28206973, 2017).
ankylosing spondylitis (11 papers, 2010 to 2025). An autoimmune chronic inflammatory disorder characterized by inflammation in the vertebral joints of the spine and sacroiliac joints. "HLA-C C1 and C2 phenotype and genotype frequencies were significantly different from controls in ankylosing spondylitis (i.e. a decrease in C1 frequency)." (PMID 20865034, 2010). "In summary, our results suggest protective effect of the presence of KIR2DS5 gene in ankylosing spondylitis, endometriosis and acute kidney graft rejection, independent from HLA-C." (PMID 20865034, 2010). "Some KIR2DS5-independent associations of ankylosing spondylitis and NSCLC with HLA-C C1 and/or C2 groups are also reported here." (PMID 20865034, 2010).
Behçet’s disease (11 papers, 2013 to 2025). "HLA‐C*03:04 has also been previously reported to protect against Parkinson disease, in which neuroinflammatory mechanisms have been implicated, and against Behçet's disease and Posner‐Schlossman Syndrome." (PMID 33991459, 2021). "In addition, we were able to find in the literature that the B*51:01:01G allele is most often mentioned in association with systemic vasculitis—Behcet’s disease, and the HLA-C*01:02 allele is associated with a higher risk of severe allergies, including to cephalosporins." (PMID 41305516, 2025). "Similar interactions have been described for Behçet’s disease (BD) and HLA-B*51, psoriasis and HLA-C*06:02, and IBD and HLA-C07." (PMID 33023259, 2020). "The most prominent of these associations concern birdshot chorioretinopathy (BSCR), ankylosing spondylitis (AS), Behçet's disease (BD) and psoriasis, which involve HLA-A*29:02, HLA-B*27, HLA-B*51, and HLA-C*06:02, respectively." (PMID 30425713, 2018).
endometriosis (11 papers, 2010 to 2024). The growth of functional endometrial tissue in anatomic sites outside the uterine body. "They showed that a genotype combination HLA-C*03:03:01 was associated with an increased risk of endometriosis (OR = 2.811, p = 0.0473), while the presence of KIR2DS2 acted as a protective factor against endometriosis with an odds ratio of 0.5577 (p = 0.0394)." (PMID 36613776, 2022). "HLA-C allele frequencies in endometriosis patients (n = 147, 294 alleles) and control patients (n = 117, 234 alleles) were determined using a sequence-based typing method." (PMID 32184413, 2020). "HLA-C is a ligand of killer cell immunoglobulin receptors (KIRs) and is an essential regulator of natural killer cell activity, which is associated with endometriosis progression." (PMID 32184413, 2020). "It is the first study addressing KIR polymorphisms and HLA-C genotypes of women with stage III or IV endometriosis in Han Chinese women." (PMID 32184413, 2020). "The presence of HLA-C*03:03:01 significantly increased the risk of endometriosis with p = 0.0473 [Odds Ratio (OR) = 2.811, 95% confidence interval (CI) = 1.021–7.738] and the statistical power was 43.8%." (PMID 32184413, 2020). "Our current findings demonstrated the association between KIR polymorphisms and HLA-C genotypes with endometriosis in women." (PMID 32184413, 2020). "Our current findings suggest that the KIR and HLA-C genotypes are associated with the pathogenesis of endometriosis." (PMID 32184413, 2020). "Moreover, to analyze the association between certain KIR-HLA-C combinations and the development of endometriosis, we characterized both KIR and HLA-C gene polymorphisms in 147 women with endometriosis and 117 controls." (PMID 32184413, 2020). "Therefore, we employed a DNA-based method for higher-resolution genotyping and investigated the association between the HLA-C genotype and endometriosis." (PMID 32184413, 2020). "We evaluated whether the HLA-C group C1 (HLA-C1) and HLA-C group C2 (HLA-C2) were associated with endometriosis." (PMID 32184413, 2020). "Herein, we analyzed the associations between HLA-C alleles and endometriosis." (PMID 32184413, 2020). "Consequently, the presence of HLA-C*03:03:01 increased the risk of endometriosis in Asian women." (PMID 32184413, 2020). "We asked whether polymorphisms in KIR, HLA-C, and HLA-B genes are risk factors for endometriosis." (PMID 25724317, 2015). "It is possible that the higher expression of HLA-C*07 due to hypermethylation of intron seven, resulted in the silencing of natural killer cells, thus promoting the occurrence of endometriosis." (PMID 39355248, 2024). "Cg03216697, cg01521131, cg09382842, and cg09556042 are only observed in the HLA-C*07 allele and are associated with higher levels of DNA methylation and gene expression of the HLA-C gene in patients with endometriosis compared to healthy controls." (PMID 39355248, 2024). "Higher methylation of intron 7 also led to higher expression of HLA-C*07 in women with endometriosis." (PMID 39355248, 2024). "We tested the association of certain KIR and HLA-C combinations and the development of endometriosis by characterizing both KIR and HLA-C genes in 147 women with endometriosis and 117 controls." (PMID 32184413, 2020). "We found that the occurrence of HLA-C*03:03*01 was increased in endometriosis than in control groups." (PMID 32184413, 2020). "In our previous paper we found an association of NK cell receptor KIR2DS5 gene and its potential ligand HLA-C C2 with endometriosis." (PMID 29234882, 2018). "Although several studies compared endometriosis with HLA-G and HLA-C,24, 25, 26 and some studies compared endometriosis to anti-tissue transglutaminase IgA,18, 19 there have been no reports so far investigating the relation between endometriosis and HLA-DQ2 and HLA-DQ8." (PMID 38432123, 2024). "A previous study revealed that the expression of HLA-C*03:03*01 was increased in endometriosis." (PMID 37662927, 2023).
endometriosis (continued). "The results suggested that HLA-C and KIR genotypes influence the susceptibility for endometriosis." (PMID 32184413, 2020). "Therefore, we attempted to investigate an association between HLA-C genotype and KIR polymorphism and the occurrence of endometriosis." (PMID 32184413, 2020). "Of the 8 HLA-C∗07 endometriosis patients, 87.5% (7/8) of patients exhibited significantly higher DNA methylation levels in the intron VII of the HLA-C gene, compared to 25.0% (2/8) in healthy women." (PMID 36974156, 2023). "This research indicated that multiple abnormal DNA methylation sites in patients with endometriosis were HLA-C∗07 specific, while the HLA-C∗07 carrier patients exhibited significantly higher DNA methylation levels at the intron VII of HLA-C compared with the HLA-C∗07 carrier healthy controls." (PMID 36974156, 2023). "However, it was seen only in HLA-C C2-positive individuals: in this group, those who possessed KIR2DS5 had 2.5 lower chance of getting endometriosis than KIR2DS5-negative women (Supplement 2)." (PMID 25724317, 2015).
HCMV infection (10 papers, 2013 to 2024). "At least for those HLA alleles detected by the applied HC10 antibody (all HLA-B and HLA-C alleles and several HLA-A alleles) this indicates a strong downmodulating effect of HCMV infection." (PMID 32596168, 2020). "Because the relevant receptor-ligand pair in this study was KIR2DL2 and (likely) HLA-C*0701, this rises the interesting possibility that the two major HLA-C*07 allotypes are differentially regulated by HCMV infection, with different effects on NK cell recognition in carriers of different alleles." (PMID 23717207, 2013). "The role of HLA-C-restricted CD8+ T cells in prevention of congenital HCMV infection and pregnancy loss could be of particular importance, because placental cells express HLA-C, but not HLA-A or -B." (PMID 23717207, 2013). "Given the relevance of congenital HCMV infections and the fact that trophoblasts do not express HLA-A and -B, but HLA-C, -G, and -E, this prompts the question as to whether US10 makes an important pathogenic contribution to placental infection, subsequent transmission to the fetus." (PMID 38900146, 2024).
prostate carcinoma (10 papers, 2013 to 2025). A carcinoma that arises from epithelial cells of the prostate gland. "CTSS and class II MHC genes were once again the most important features, though HLA-B and HLA-C appeared more influential in prostate cancer risk." (PMID 37173324, 2023).
acute myeloid leukemia (9 papers, 2013 to 2025). Acute myeloid leukemia (AML) is a group of neoplasms arising from precursor cells committed to the myeloid cell-line differentiation. "Among these alleles, the existing literature highlights associations between aplastic anemia and HLA-B*49:01:01, acute myeloid leukemia and HLA-C*07 and childhood common acute lymphoblastic leukemia and HLA-DPB1*02:01." (PMID 39329950, 2024). "The use of allogeneic NK cells has shown substantial clinical benefit against acute myeloid leukemia (AML) after haploidentical, partially mismatched, hematopoietic cell transplantation, when HLA-C incompatibility existed in the graft-versus-host (GVH) direction." (PMID 23483943, 2013).
pancreatic cancer (9 papers, 2019 to 2025). "Nevertheless, WDR5 expression exhibits a positive correlation with HLA level in human cancer cells, and H3K4me3 enrichment is found at the promoter regions of the HLA-A, HLA-B, and HLA-C genes in pancreatic cancer cells based on an Encode database analysis." (PMID 39201460, 2024). "Murine PBMCs transduced with reactive TCRs that recognize HLA-C*11:01–expressing pancreatic cancer cells were evaluated in a pancreatic cancer xenograft mouse model." (PMID 35014625, 2022). "However, WDR5 expression is positively correlated with the HLA level in human cancer cells, and H3K4me3 enrichment is observed at the promoter region of the HLA-A, HLA-B, and HLA-C genes in pancreatic cancer cells." (PMID 39201460, 2024). "Using flow cytometry, we monitored MHC class I expression with the BB7.2 antibody that recognizes peptide-bound HLA-A2 (an MHC class I molecule that is expressed by S2-013 pancreatic cancer cells), and with an antibody that recognizes HLA-B and HLA-C (B1.23.2)." (PMID 36126055, 2022). "To determine if the expression of MHC class I heavy chain proteins in pancreatic cancer cells is increased by M344 treatment, we performed immunoblot analysis on lysates of M344-treated S2-013 pancreatic cancer cells with an antibody recognizing the human MHC class I heavy chains HLA-B and HLA-C." (PMID 36126055, 2022).
tuberculosis (9 papers, 2007 to 2025). A chronic, recurrent infection caused by the bacterium Mycobacterium tuberculosis. "Researchers have studied the relationship among HLA‐B, HLA‐C and KIR genotypes, HIV‐1 infection, and immune reconstitution inflammatory syndrome (IRIS) in tuberculosis and HIV‐coinfected patients." (PMID 33657268, 2021).
autism (8 papers, 2014 to 2023). Persistent deficits in social interaction and communication and interaction as well as a markedly restricted repertoire of activity and interest as well as repetitive patterns of behavior. "None of the HLA-C alleles frequencies shows any significant association with autism among Saudi patients." (PMID 24672722, 2014).
Graves disease (8 papers, 2007 to 2023). Graves' disease is an autoimmune disorder that leads to overactivity of the thyroid gland (hyperthyroidism).It is caused by an abnormal immune system response that causes the thyroid gland to produce too much thyroid hormones. "Another example is Graves’ disease, where individuals with HLA-C*03:02 allele were more susceptible to acquiring a methimazole-induced liver injury." (PMID 37465164, 2023). "The Graves’ disease (GD) risk allele of rs1521 variant is primary associated with a reduced expression of HLA-C gene, ligand of CD158b, in thyroid cells." (PMID 32182948, 2020). "It has been reported that HLA-C*07:02 is a risk factor for Graves disease." (PMID 28066418, 2016). "Besides MHC class I and II, a recent study found “a novel and major association of HLA-C in Graves' disease that eclipses the classical HLA-DRB1 effect”." (PMID 21738647, 2011). "Specifically, genetic variants, rs1521 and rs3094228, associated with Graves’ disease and TPOAb-positivity, alter the expression of thyroid cell-expressed ligands, MIC-A, MIC-B, and HLA-C, known to recognize CD314 and CD158b immunoreceptors expressed on NK cells." (PMID 32182948, 2020).
lung adenocarcinoma (8 papers, 2017 to 2025). A carcinoma that arises from the lung and is characterized by the presence of malignant glandular epithelial cells. "There was one variant on major histocompatibility complex I gene HLA-C with one case of lung adenocarcinoma (HLA-C G276 V) and another mutation found on colon adenocarcinoma (HLA-C G276R)." (PMID 31438887, 2019). "We therefore investigated tumors with six distinct HLA alleles and loss of one HLA haplotype (HLA-A, HLA-B, and HLA-C) in at least one tumor region (n = 20; 9 lung adenocarcinomas and 11 lung squamous cell carcinoma)." (PMID 29107330, 2017). "Indeed, a recent study demonstrated increased NK cell infiltration in tumor regions of lung adenocarcinoma patients strongly associated with loss of heterozygosity (LOH) at the HLA-C locus compared to tumor regions without HLA-C LOH." (PMID 31623687, 2019). "A particular study revealed that MHC-I molecules, encompassing HLA-B and HLA-C, exhibited reduced expression in lung adenocarcinoma patients who were non-smokers compared to those who smoked." (PMID 38672772, 2024).
multiple myeloma (8 papers, 2004 to 2024). "The positive association of multiple myeloma (MM) risk with HLA-C loci C*07:02 g and C*02:02 g, and the negative association of that with C*05:01 g were statistically significant in Whites have recently been reported." (PMID 30155344, 2018).
neuroblastoma (8 papers, 2017 to 2025). Neuroblastoma (NB) is the most common solid, extracranial childhood tumor. "Similar cytotoxicity results were obtained against neuroblastoma cell lines which also vary by KIR ligand HLA-C expression although HLA class I expression is generally low in these cells." (PMID 33178188, 2020). "By contrast, neuroblastoma had low levels (HLA-A 6.5; HLA-B 1.0; HLA-C 3.4)." (PMID 41312385, 2025). "We next searched the neuroblastoma immunopeptidomics dataset we created for peptides derived from the MYCN oncogene, a major cancer driver in neuroblastoma, finding only a single peptide (KATEYVHSL) presented on the relatively rare HLA-C*16:01 allele representing <5% of the population." (PMID 32256484, 2020).
allergic disease (7 papers, 2013 to 2026). An immune response that occurs following re-exposure to an innocuous antigen, and that requires the presence of existing antibodies against that antigen. "Accordingly, as an intrinsic abnormality, impaired HLA-C-mediated triggering of protective immunity to microbial exposure would predispose an individual to increased levels of total serum IgE as a principal determinant of allergy." (PMID 24324648, 2013). "Finally, it is also interesting to note that 1 locus (rs9266772) near HLA-C and MICA has been recently identified as one of the loci of allergy-specific susceptibility." (PMID 24324648, 2013).
dengue (7 papers, 2013 to 2025). "The HLA type of the HLA-A, HLA-B, HLA-C, HLA-DR, and HLA-DQ loci of the 187 confirmed dengue of DENV-3 genotype III was determined in low resolution." (PMID 23818909, 2013).
gastric cancer (7 papers, 2018 to 2025). A primary or metastatic malignant neoplasm involving the stomach. "Our previous work has shown that the epitopes of this mutation can be presented by multiple HLA molecules (e.g., HLA-C07:02, HLA-C 07:01, HLA-A30:01, and HLA-B58:01) and can be a potential neoantigen in patients with gastric cancer." (PMID 32733937, 2020).